STIM1 (stromal interaction molecule 1)
Diseases named in the same sentence as STIM1 in open-access papers (continued):
Sharing a sentence is not in itself a finding about the gene and the disease.
temporal lobe epilepsy (1 paper, 2020). A localization-related (focal) form of epilepsy characterized by recurrent seizures that arise from foci within the temporal lobe, most commonly from its mesial aspect. "Accordingly, the expression of both STIM1 and STIM2 is highly increased in hippocampal specimens of a patient with temporal lobe epilepsy." (PMID 32315120, 2020).
thrombosis (1 paper, 2020). "These genes included STIM1 and C4BPA, which impact platelet reactivity and/or thrombosis risk, as well as MASTL and TPM4, which influence megakaryo-thrombopoiesis." (PMID 32600345, 2020).
trigeminal neuralgia (1 paper, 2024). Trigeminal neuralgia is a nerve disorder that causes a stabbing or electric-shock-like pain in parts of the face. "However, this study, for the first time, explicitly associates the role of STIM1 with the pathological processes of trigeminal neuralgia, which is of importance for our understanding of the pathogenesis of trigeminal neuralgia." (PMID 38962804, 2024). "Our experimental results indicate that compared to TN (trigeminal neuralgia) rats, the TN + shRNA STIM1 group showed partial relief in mechanical allodynia and thermal hyperalgesia latency." (PMID 38962804, 2024). "We confirm that the STIM1 gene promotes the occurrence of trigeminal neuralgia by regulating the SOCE pathway and releasing inflammatory factors in T lymphocytes." (PMID 38962804, 2024). "In conclusion, the experimental results indicate that STIM1 promotes trigeminal neuralgia by mediating store-operated calcium entry to regulate the release of inflammatory factors in T lymphocytes." (PMID 38962804, 2024). "Secondly, although we have found that STIM1 plays a crucial role in developing trigeminal neuralgia, we still need a deeper understanding of its specific mechanism of action." (PMID 38962804, 2024). "In our study, bioinformatics analysis revealed the upregulation of the STIM1 gene in patients with trigeminal neuralgia, indicating its role in the occurrence and development of trigeminal neuralgia." (PMID 38962804, 2024). "Looking ahead, we will continue to investigate the specific mechanism of the role of STIM1 in trigeminal neuralgia and explore its potential as a therapeutic target for trigeminal neuralgia." (PMID 38962804, 2024). "By analyzing the gene expression differences of patients with trigeminal neuralgia using bioinformatics tools, we discovered the high expression of the STIM1 gene in such patients, suggesting its potential key role in the occurrence and progression of the disease." (PMID 38962804, 2024). "In summary, our results indicate that the upregulation of STIM1 expression may play an essential role in the pathogenesis and progression of trigeminal neuralgia." (PMID 38962804, 2024). "However, this study is the first to reveal that STIM1 affects the release of inflammatory factors in T lymphocytes, thus impacting the occurrence of trigeminal neuralgia and providing new insights for its treatment." (PMID 38962804, 2024). "Therefore, we analyzed the role of STIM1 in store-operated calcium entry (SOCE) in the trigeminal ganglion of trigeminal neuralgia rats." (PMID 38962804, 2024). "In addition, we have also demonstrated that STIM1 plays a vital role in the development of trigeminal neuralgia by regulating the calcium store-operated calcium entry (SOCE) pathway and promoting the release of inflammatory cytokines in T lymphocytes." (PMID 38962804, 2024). "Therefore, drugs targeting STIM1 or the SOCE pathway may become a new approach for treating trigeminal neuralgia." (PMID 38962804, 2024). "Therefore, we further investigated whether STIM1 could regulate trigeminal neuralgia by modulating the release of inflammatory cytokines in T lymphocytes." (PMID 38962804, 2024). "Therefore, we speculate that STIM1 promotes the specific mechanism of trigeminal neuralgia by regulating SOCE." (PMID 38962804, 2024). "Our experimental results indicate that STIM1 promotes the release of inflammatory factors in T lymphocytes by mediating SOCE, thereby influencing the occurrence of trigeminal neuralgia." (PMID 38962804, 2024). "This study presents novel evidence that STIM1 is a key regulator of SOCE and inflammatory cytokine release in T lymphocytes, contributing significantly to the pathogenesis of trigeminal neuralgia." (PMID 38962804, 2024).
trigeminal neuralgia (continued). "This investigation aims to elucidate the novel role of Stromal Interaction Molecule 1 (STIM1) in modulating store-operated calcium entry (SOCE) and its subsequent impact on inflammatory cytokine release in T lymphocytes, thereby advancing our understanding of trigeminal neuralgia (TN) pathogenesis." (PMID 38962804, 2024).
tuberous sclerosis complex (1 paper, 2019). "A recent study showed an interesting relationship between mTORC1 and STIM1 expression as a novel potential therapeutic approach for patients with tuberous sclerosis complex (TSC) tumors." (PMID 30935064, 2019).
urolithiasis (1 paper, 2021). Stone(s) within the urinary tract. "However, both variants were in linkage equilibrium (uncorrelated) with another STIM1 variant rs12290747 (r2 = 0.004) that was found to be significantly associated with urolithiasis in a recent, large-scale Japanese population GWAS." (PMID 34074324, 2021).
Wilms kidney tumors (1 paper, 2019). "In addition, STIM1 expression in Wilms kidney tumors is regulated at the transcriptional level by the zinc-finger proteins Wilms tumor suppressor 1 and early growth response." (PMID 31506588, 2019).
Zinc deficiency (1 paper, 2024). A deficiency of the essential metal Zinc; an essential cofactor for many enzymes. "We found a significantly increase in STIM1 expression due to zinc deficiency." (PMID 38807213, 2024).
cancer (134 papers, 2008 to 2026). A tumor composed of atypical neoplastic, often pleomorphic cells that invade other tissues. "Functionally, we have unveiled a splicing variant of STIM1 that shows a relatively high expression in certain types of cancer cells." (PMID 35076181, 2022). "A possible causative role of STIM1 elevation in different types of cancer makes it an attractive chemotherapeutic target." (PMID 36556285, 2022). "The overexpression of Orai1/STIM1 was paralleled by the enhancement of Akt1, a serine/threonine kinase implicated in cancer cell proliferation, inhibition of apoptosis, and establishment of therapy resistance." (PMID 35207698, 2022). "This is due to either altered expression of CRAC channel proteins, specifically, STIM1/STIM2, Orai1, and Orai3 in cancer cells compared with healthy cells or mutations in STIM1 or Orai1 proteins." (PMID 36612099, 2022). "We previously found that the expression level of STIM1 is significantly associated with the risk of cancer metastasis and survival, and blockade of SOCE activity inhibits tumor angiogenesis and growth in animal models." (PMID 34803742, 2021). "Different STIM1 variants lead to dissimilar patterns of STIM1 aggregation and trafficking, and which were associated with alterations of Ca2+ influx, and subsequent cancer cell migration." (PMID 34803742, 2021). "Altogether, we generated novel insight into the role of STIM1 during SOCE activation, and uncovered the impact of real-world STIM1 variants on cancer cells." (PMID 34803742, 2021). "In this study, we transfected real-world STIM1 variants located on Ca2+ binding or microtubule interacting domains to study their impacts on cancer cell migration." (PMID 34803742, 2021). "After establishing the impact of different STIM1 variants on cancer cell migration, we further used dSTORM imaging to address STIM1 ER-plasma membrane trafficking in SiHa cells with p.D76G, p.D84Y, and p.R643C variants." (PMID 34803742, 2021). "We constructed a comprehensive molecular model of STIM1 activation, providing the structural and functional insights into the fundamental Ca2+ homeostasis, and uncovering the impact of STIM1 variants on cancer cell behavior." (PMID 34803742, 2021). "We also generated the real-world STIM1 variants adapted from the Catalogue of Somatic Mutations in Cancer (COSMIC) database to study their impact on SOCE, and the subsequent alterations of cancer cell behaviors." (PMID 34803742, 2021). "Knockdown of STIM1 or Orai1 in various cancer cells is associated with inhibition of cell migration, with some exceptions." (PMID 34069353, 2021). "We generated STIM1 variants adapted from a real-world database and introduced them into SiHa cells to clarify the impact of STIM1 mutations on cancer cell behavior." (PMID 34803742, 2021). "We demonstrated that somatic mutations of STIM1 differentially regulate cancer cell migration by changing the turnover of focal adhesion." (PMID 34803742, 2021). "For example, several cancers have been associated with upregulated expression of STIM1, STIM2, or Orai1 and increased SOCE." (PMID 29783744, 2018). "The store-operated calcium (Ca2+) entry (SOCE) and its major mediator Stim1 have been shown to be implicated in a number of pathological processes typical for cancer." (PMID 28326487, 2017). "Stromal interaction molecule 1 (STIM1) is a factor associated with cancer progression that is upregulated in highly invasive CRC cell lines and tissues, and promotes cell metastasis both in vitro and in vivo." (PMID 26307974, 2015). "While genetic mutations in Orai1 or STIM1 were linked to immune disorders, skeletal muscle myopathy and heart hypertrophy, the functions of these genes in various types of cancer have fascinated many investigators." (PMID 25481035, 2015). "Taken together, these studies suggest a potential role for STIM1 protein as a diagnostic biomarker to predict the occurrence, progression or prognosis of cancer patients." (PMID 23594099, 2013).
cancer (continued). "As a result, these findings, suggest that the potential impact of STIM1 polymorphisms should be investigated in cancer patients to learn whether these mutations play a role in this novel function." (PMID 38224453, 2024). "Growing evidence supports the hypothesis that STIM1 and Orai1 are implicated in a number of pathological processes in cancer, including human glioblastoma invasion, acute myeloid leukemia cell migration, and breast tumor cell migration." (PMID 35207698, 2022). "Not only Orai1 but also STIM1 can be a cause of cancer development." (PMID 35681544, 2022). "However, SOCE can be enhanced in cancer cells due to an increase in the expression and/or function of its underlying molecular components, i.e., STIM1 and Orai1." (PMID 35884372, 2022). "In addition, more cancer-associated STIM1 mutations have been reported in The Cancer Genome Atlas (TCGA) database without functional annotations." (PMID 32098964, 2020). "Indeed, altered expression of STIM1 and Orai1 is a hallmark of many cancer types, suggesting their potential value as prognostic biomarkers in cancer." (PMID 31366337, 2019). "Enhanced expression of STIM1 in cancer tissue has been associated with poor patient prognosis." (PMID 31366337, 2019). "Importantly, the STIM1 mutational pattern might have an impact on cancer metastasis and therefore might be a prognostic marker, and inhibitors of STIM1 are a potential treatment option for cancer patients." (PMID 34803742, 2021). "However, few studies have addressed the impact of STIM1 mutations on cancer cell biology." (PMID 34803742, 2021). "Similar approaches have been proposed for targeting other calcium signaling regulators, such as STIM1 and Orai1, in cancer therapy." (PMID 40362663, 2025). "On the other hand, CRC cancer cells exhibit downregulated expression of STIM2 leading to a greater STIM1:STIM2 ratio that supports enhanced SOCE." (PMID 38514909, 2024). "Cross‐referencing these datasets identifies NCX1, TRPC1, TRPC5, TRPM7, TRPM8, TRPML3, ORAI1/STIM1 and IP3R1 as cancer‐associated Ca2+ transporters regulated by S‐acylation via known enzyme(s)." (PMID 39429488, 2024). "Elevated ROS from mitochondrial dysfunction can promote cancer cell proliferation by activating HIF1α and stimulating calcium signaling through STIM1 and SOCE." (PMID 39104527, 2024). "SOCE core proteins, the ER Ca2+ sensor STIM1 and the CRAC channel subunit Orai1, have been associated with cancer progression and metastasis." (PMID 39061158, 2024). "Intracellular alkalization, or deprotonation at H355-H407, can directly activate the molecule, while acidic conditions render it less active, potentially impairing STIM1-dependent functions in cancer cells characterized by a lower pH." (PMID 39454952, 2024). "The expression of STIM1 and ORAI1 was first evaluated in cytospins of spiked PC-3 and DU-145 cancer cells with PBMCs by immunofluorescence using antibodies against CK, STIM1, and ORAI1." (PMID 38903530, 2024). "The prognostic significance of STIM1 and its regulation of tumor cells has been demonstrated in a variety of cancers and is a hot topic of research in the field of oncology." (PMID 37932320, 2023). "Recently, it has become increasingly clear that STIM1 is involved in regulating the occurrence, development, invasion, and metastasis of a variety of cancers." (PMID 37932320, 2023). "Recent studies have shown that STIM1 or Ca2+ signaling can regulate apoptosis, autophagy, pyroptosis, and ferroptosis in tumor cells and act discrepantly in different cancers." (PMID 37932320, 2023). "STIM1-mediated SOCE has been found to support various cancer hallmarks, including cell viability, migration and metastasis, but the mechanism of STIM1 upregulation is not fully understood." (PMID 37542345, 2023). "STIM1 and SOCE are linked to angiogenesis and cancer cell survival, both indicating tumor aggressiveness and poor prognosis." (PMID 36556285, 2022).
cancer (continued). "Elevated levels of STIM1, an endoplasmic reticulum Ca2+ sensor/buffering protein, appear to be correlated with poor cancer prognosis in which microRNAs are also known to play critical roles." (PMID 36556285, 2022). "All of these studies demonstrated that overexpression of STIM1 and Orai1 conferred chemoresistance to a number of cancers." (PMID 35207698, 2022). "Further, STIM1 expression is augmented in a plethora of pathological conditions including vascular disease, asthma, and several types of cancer." (PMID 36356899, 2022). "Among the STIM1 mutants identified to occur in cancer, several (STIM1 H72R, D76V, D78G, A79T, N80K, E87Q, L92P) are located in the canonical EF hand and the hydrophobic cleft and have been found to trigger constitutive activation." (PMID 36612099, 2022). "The expression of important markers of EMT and requisite regulators of mesenchymal cell migration, such as vimentin or fibronectin, is downregulated in esophageal and gastric cancer upon STIM1 and/or Orai1 silencing." (PMID 36612099, 2022). "Orai3 is a calcium channel activated by Stim1 or Stim2,9 but in further studies, Orai3 interacted with Orai1 to form a heteromer was recognized in cancer cells for proliferation and decreased apoptosis." (PMID 36128650, 2022). "In particular, for SK channels as well as their interplay with STIM1/Orai1, the detailed links to various cancer signaling pathways are insufficiently described." (PMID 36612099, 2022). "Several other cancer-related mutants are located in the STIM1 C-terminus, which is essential in both maintaining the quiescent state and establishing CRAC channel activation." (PMID 36612099, 2022). "In the case of STIM1/2-deficient cells, the increased survival of mice was associated with the defective ability of T-ALL cells to activate cancer-induced inflammation." (PMID 34234374, 2021). "In summary, different STIM1 variants lead to dissimilar Ca2+ influxes during SOCE, which impact STIM1 dynamics and cancer cell migration." (PMID 34803742, 2021). "We first analyzed the Gene Expression Omnibus (GEO) dataset to determine the relationship between STIM1 expression levels and cancer progression." (PMID 35008585, 2021). "A higher expression of STIM1 has been suggested to correlate with poor prognosis and survival in many cancers." (PMID 34155535, 2021). "On the other hand, STIM1 in vivo overexpression in cancer cells positively correlates with increased VEGF secretion, endothelial cell proliferation, and thus angiogenesis." (PMID 34572262, 2021). "It should be attentive to recommend the patients with cancer taking anti-cancer drugs acting on STIM1-mediated SOCE with synergistic effect." (PMID 33867841, 2021). "Stromal Interaction Molecule 1-dependent signaling plays an important role in cancer cell growth, migration, and angiogenesis." (PMID 34803742, 2021). "Recently, many studies have found that STIM1 is essential for cancer cell migration, invasion, and metastasis." (PMID 35008585, 2021). "STIM1 has been reported to regulate the cancer cell growth, proliferation, and migration, and it has been found to be upregulated in a variety of cancers." (PMID 35008585, 2021). "This study provides the rational theoretical basis for how inhibitors targeting the STIM1-Orai1 pathway suppress amoeboid-like movements of cancer cells and consequently inhibit invasion." (PMID 33473127, 2021). "There is significant interest in the literature in the role of SOCE in cancer progression and metastasis with implication on the role of STIM1 and Orai1 in cell migration." (PMID 34069353, 2021). "Histological studies of cancer cells show that patients with higher STIM1 expression have bigger tumors with higher nerve invasion." (PMID 34205590, 2021). "By altering the focal adhesion turnover, actomyosin contractility, and invadopodia formation of cancer cells, the expression of STIM1 promotes tumorigenesis and tumor metastasis in different types of cancers." (PMID 34803742, 2021).